C4orf50 (chromosome 4 open reading frame 50)
Synonyms: FLJ46481
Tractability: No criterion of Open Targets' tractability assessment is met for any kind of drug.
Gene: Protein-coding gene on chromosome 4 (5,897,373 to 6,200,555, reverse strand). Ensembl gene ENSG00000181215.
Genetic constraint (gnomAD): Loss-of-function variants: 77 observed, 73.44 expected, observed/expected ratio (o/e) 1.05, 90% interval 0.87 to 1.27. The upper end of that interval is the gene's LOEUF score, 1.27, which puts it in group 5 of 6, group 1 being the genes least tolerant of losing a copy. Missense variants: 1,216 observed, 1,116.2 expected, observed/expected ratio (o/e) 1.09, 90% interval 1.04 to 1.14. Synonymous variants: 514 observed, 456.54 expected, observed/expected ratio (o/e) 1.13, 90% interval 1.05 to 1.21.
Homologues: Orthologues: chimpanzee C4H4orf50 (98% identical), dog C4orf50 (57% identical), pig C8H4orf50 (46% identical), mouse Gm1043 (45% identical), rat C14h4orf50 (45% identical).
Diseases named in the same sentence as C4orf50 in open-access papers:
C4orf50 is named in the same sentence as 2 diseases in open-access papers, as found by Europe PMC text mining. Sharing a sentence is not in itself a finding about the gene and the disease. The quoted sentences say what the papers report.
Alzheimer disease (1 paper, 2022). A progressive, neurodegenerative disease characterized by loss of function and death of nerve cells in several areas of the brain leading to loss of cognitive function such as memory and language. "Its orthologs (human C4orf50) was highly expressed in brain tissues and related to Alzheimer’s disease and diabetes." (PMID 36456907, 2022).
C4orf50 also shares sentences with these, for which no sentence is quoted: diabetes (1 paper).